ATM (ATM serine/threonine kinase)
Diseases named in the same sentence as ATM in open-access papers (continued):
Sharing a sentence is not in itself a finding about the gene and the disease.
colon carcinoma (continued). "In summary, in the current study, we find that PXR confers resistance of liver and colon cancer cells to IR-induced DNA damage stress through stabilization of ATF3, thus promoting ATF3-mediated ATM activation." (PMID 35372071, 2022). "In addition to the fact that MSI is associated with downregulation of MRE11 in colon cancer cells, which is essential for optimal signaling of ATM in response to DSBs, HCT116 cells also carry a mutation (c3380C > T) in one ATM allele, affecting ATM expression to half of normal." (PMID 33888065, 2021). "The expression of ATM in tumors located in rectum was lower compared to its adjacent mucosa, in contrast to ATR, which showed a significant increased expression in colon cancer relative to its adjacent mucosa." (PMID 29870526, 2018). "Notably, however, it remains unclear whether the ATR and/or ATM checkpoint pathways play important roles in determining the survival of human colon cancer cells, the cells that are targeted by 5-FU and FdUrd in patients, when they are treated with these agents." (PMID 22194930, 2011). "The modulation of ATM expression by GPER in low oxygen tension and the sensitivity of its expression to oestrogen in CRC provides an additional mechanism for protumorigenic actions of oestrogen via GPER in colon cancer under hypoxic conditions." (PMID 38137047, 2023). "p-ATM was increased in 27 out of 40 colon cancer tissues when compared with their matched controls, whereas total ATM was not changed in cancer." (PMID 32203529, 2020). "Over-expression of miR-18a in colon cancer cells significantly reduced the luciferase activity of the construct with wild-type ATM 3′UTR but not that with mutant ATM 3′UTR, inferring a direct interaction of miR-18a with ATM 3′UTR." (PMID 23437304, 2013). "Also, ATM and CHK2 form a complex with circadian protein PER1, and it was further demonstrated that PER1 knockdown reduced ATM-mediated CHK2 phosphorylation and dampened apoptotic response to DNA damage in human colon cancer cell line HCT116 (Geryet al., 2006)." (PMID 39282509, 2023). "Furthermore, expression of ATM was significantly lower in rectum tumor compared to its adjacent tissue, whereas almost no change in its expression between colon cancer and its adjacent mucosa." (PMID 29870526, 2018). "To determine which factor plays a role in baicalin-induced senescence in colon cancer cells, we tested the level of reactive oxidative species (ROS) and the activity of superoxide dismutase (SOD), as well as the protein levels of γH2AX and p-ATM in HCT116 tumor cells treated with baicalin." (PMID 29440765, 2018). "Notably, however, depletion of ATM or ATR does not sensitize colon cancer cells to 5-FU, whereas these checkpoint pathways promote the survival of cells treated with FdUrd, suggesting that FdUrd exerts cytotoxicity by disrupting DNA replication and/or inducing DNA damage, whereas 5-FU does not." (PMID 22194930, 2011).
leukemia (71 papers, 2004 to 2025). A malignant (clonal) hematologic disorder, involving hematopoietic stem cells and characterized by the presence of primitive or atypical myeloid or lymphoid cells in the bone marrow and the blood. "Four drug classes overlapped between both sets of Setd2-deficient leukemia signatures, including ATM/ATR-i, BET-i, BTK-i, and G9a-i." (PMID 40300107, 2025). "Loss of ATM or inhibition of ATM kinase activity disrupts this axis and leads to exhaustion of LSCs and leukaemia cells in MLLr-AML." (PMID 38671157, 2024). "ATM is encoded by an mRNA sequence containing approximately 13k base pairs, which hinders the overexpression of ATM in leukaemia cells but is feasible in 293T cells." (PMID 38671157, 2024). "All three 11q22.3 deletions involving ATM (sizes: 16, 17, and 18 Mb) also encompassed at least two of the other nearby leukemia-associated genes (BIRC3, ZBTB16, KMT2A, or CBL)." (PMID 36831635, 2023). "More recently, ATM germinal and somatic mutations were also found in multiple types of cancer, such as leukemia, lymphoid malignancies, or solid tumors that show a chemotherapy resistance and adverse prognosis." (PMID 34771661, 2021). "ATM deficiency also causes 11q23 chromosome translocations—the most frequent chromosome abnormality in secondary leukemia." (PMID 34198619, 2021). "The ATM gene plays an essential role in cell cycle control and repair of DNA damage after DNA double strand breaks and inactivation of ATM is responsible for T-cell lymphopenia and increased risk for T-cell lymphoma/leukemia." (PMID 31849966, 2019). "Previously, we showed that ATM deficiency led to the 11q23 chromosome translocation, the most frequent chromosome abnormalities in secondary leukemia." (PMID 29759113, 2018). "Mutations in ATM pre-dispose A-T patients to the development of lymphoid neoplasms, with a risk for leukemia approximately 70 times higher than the normal population." (PMID 28356161, 2017). "Third, a pathogenic role of altered ATM function was proposed, when a germline missense ATM mutation was detected in the phosphatidylinositol-3 (PI-3) kinase coding region of a pediatric leukemia patient with MLL rearrangement." (PMID 26161385, 2015). "It has also been hypothesized that haploinsufficient ATM causes the removal of DNA repair genes and promotes carcinogenesis in leukaemia cells." (PMID 37020276, 2023). "However, since ATM mutations are associated with a high incidence of leukemia in childhood, she possibly carried the variant as well." (PMID 34357098, 2021). "ATM mutations have been reported in adult sporadic lymphoma and leukaemia." (PMID 14735203, 2004). "A previous study demonstrated that the loss of ATM did not impact the development of murine AML driven by MLL-AF9 in primary transplants; however, the inhibition of ATM significantly alleviated the disease burden and extended the survival of leukaemia mice." (PMID 38671157, 2024). "In the present study, CBP is rapidly degraded by the proteasome in MLLr leukaemia, and S5178 phosphorylation by ATM confers CBP stability." (PMID 38671157, 2024). "In contrast, no change in the mRNA level of DOT1L was found in mouse Atm−/− LSCs or in human ATM knockdown MLLr leukaemia cells." (PMID 38671157, 2024). "BRCA2 accounts for 50% (7/14), with P/LP variants including a variety of tumors in relatives such as breast, thyroid, bone, gastric, prostate, leukemia, and esophagus, followed by ATM, in 3/14 (21.4%), which referred on thyroid, gastric, and brain cancers." (PMID 38890714, 2024). "Our study indicated that ATM is essential for the long-term maintenance of leukaemia stem cells (LSCs) in MLLr-AML." (PMID 38671157, 2024). "For example, PRMT5 regulation of POLD1 and ATM via AS have been previously suggested by us and others in leukemias and uveal melanomas." (PMID 37861290, 2023).
leukemia (continued). "Family history of leukemia was observed in patients carrying a VUS in the ATM, BRCA1 and BRCA2 genes." (PMID 37277882, 2023). "In contrast, recent studies have shown that in BRCA-proficient leukemia cells, inhibition of the TGFβ pathway promotes a reduction in ATM, BRCA1 and BRCA2 and a concomitant increase in olaparib sensitivity." (PMID 34871431, 2021). "It is known that all A-T patients with mild phenotype and less activity of ATM are prone to the development of tumors, especially leukemia." (PMID 34771661, 2021). "Our experimental results show that after treatment with Stattic, the level of ATM mRNA in leukemia cells is lower, and after Stattic and VP-16 treatment of cells, the expression of BRCA1, BARD1, RAD51, and polδ in the HR pathway are all downregulated." (PMID 33796529, 2021). "Alterations in the function of ATM play pathologic roles in the development of leukemia/lymphoma and cancer." (PMID 29759113, 2018). "Inhibition of ATM with an orally applicable compound is currently subject to phase 1 clinical evaluation and has shown activity in a murine leukaemia model." (PMID 29939287, 2018). "Taken together with these findings, our resultssuggest that increased sensitivity to TOP2 inhibitors caused by mutations or defectsof ATM pathways leads to KMT2A rearrangement, ultimately resultingin the development of infant leukemia." (PMID 26657054, 2015). "Building on the previous evidence, we demonstrated that in L1210 murine leukemia cell line the rate limiting enzyme in dN salvage, dCK, is activated via phosphorylation at Ser74 by ATM in response to oxidative stress and IR-induced DNA damage." (PMID 25101980, 2014). "Altered function of ATM plays pathologic roles in the development of leukemia/lymphoma and cancer including leukemia with MLL translocations." (PMID 21048951, 2010). "On the other hand, mutated DOT1L mimicking constitutive acetylation (K358Q) can rescue the growth deficiency of MLLr leukaemia cells with ATM loss, which validates our speculation that DOT1L serves as a downstream target of ATM." (PMID 38671157, 2024). "Importantly, preclinical PRMT5 inhibitors increase DNA damage and improve the sensitivity of leukemia cells to PARP or ATM inhibitors in vitro." (PMID 37861290, 2023). "It is important to note that ATM-mediated regulation of mTOR protein levels does not appear to be unique to FLT3-dependent AMLs or leukemia in general, as implicated with our analyses of other cell types." (PMID 36259537, 2022). "We observed that the ATM gene is connected with maximum number of diseases including respiratory infections, liver carcinoma, Bronchiectasis, diabetes, cellular immunodeficiency, fever, leukemia, fibrosis in the network compare to other HubGs." (PMID 35390032, 2022). "Leukemia cells with MLL-rearrangements also respond to ATM inhibitors." (PMID 34594227, 2021). "It was recently shown that TGFβ signaling promotes the expression of ATM in K562 leukemia cells." (PMID 34871431, 2021). "Notably, RSV induced ATM activation is accompanied by S phase arrest in ovarian tumor cells, malignant B cells and leukemia cells." (PMID 28950914, 2017). "Correspondingly, Topo1 inhibitor selectively eradicates Notch1-driven AtmKD/- leukemia, but not the isogenic parental Atm proficient leukemia, identifying Topo1 inhibitors as a targeted therapy for human cancers carrying missense ATM kinase domain mutations." (PMID 27304073, 2016). "In addition, dysfunction of ATM plays an important role in thedevelopment of infant leukemia in certain cases." (PMID 26657054, 2015). "In a murine leukemia cell line, we confirm that ATM phosphorylates dCK after IR at Ser74." (PMID 25101980, 2014). "Several studies have indicated that ATM may also be involved in the development of some subtypes of sporadic lymphoma and leukaemia." (PMID 14735203, 2004).
leukemia (continued). "In a previous study involving leukemia cells, we showed that in the presence of DSB damage, peposertib disrupts a negative regulatory loop between DNA-PK and ATM." (PMID 38791158, 2024). "The present study revealed that the ATM-CBP-DOT1L axis regulates the maintenance of MLLr-AML LSCs and leukaemia cells through sequential protein posttranslational modifications." (PMID 38671157, 2024). "To investigate the role of ATM in human MLLr-AML, we knocked down ATM in MLL-AF9 (MOLM-13) and MLL-AF4 (MV4-11) leukaemia cells via a lentivirus-based shRNA expression technique." (PMID 38671157, 2024). "Our study has revealed that CREB binding protein (CBP) is a linker between ATM and DOT1L that sustains MLLr leukaemia." (PMID 38671157, 2024). "Previous study has shown that SETD2-mutant leukemia exhibits reduced phosphorylated ATR, indicating impaired DDR; however, the efficacy of ATM/ATR-i in SETD2-mutant leukemia remains unknown." (PMID 40300107, 2025). "In this study, we report that SF3B1 mutation triggers genomic instability through excessive global and centromeric R-loop accumulation and ATM deletion further exacerbates the dysregulation of this process, ultimately resulting in CIN and possibly contributing to the initiation of leukemias." (PMID 37463047, 2023). "Dyskerin is an essential nucleolar protein that can affect the growth of tumors through its related mechanism of rRNA processing in the precursor; the rRNA synthesis inhibitor CX-5461 can induce acute lymphocytes by activating the ATM/ATR pathway, leukemia cells stagnate and die." (PMID 35178347, 2022). "However, the branches of the ATM pathway, ILK signaling, NGF, PPAR and VEGF pathways were regulated oppositely in the adult and pediatric leukemia samples." (PMID 27870639, 2016). "Also, in our leukemia model, ERG under-expressed genes included ATM, CHEK1 and ATR, which are key genes in the initiation of homology-dependent DNA repair." (PMID 24504051, 2014). "We identified the phosphorylation of CBP by ATM, which confers the stability of CBP by preventing its proteasomal degradation, and characterised the acetylation of DOT1L by CBP, which mediates the high level of H3K79me2 for the expression of leukaemia genes in MLLr-AML." (PMID 38671157, 2024). "In addition, in a clinical context modulation of EVI1-mediated gene expression by genotoxic stress and ATM, for example in response to chemotherapy, is likely to be relevant for gene expression patterns in EVI1-expressing leukaemia and solid tumors also in patient samples." (PMID 29939287, 2018). "In sum, these results utilizing a murine leukemia cell line model and human A-T LCLs confirm that the activation of dCK in response to IR is ATM-dependent, and demonstrate that dCK activation is likely not carried out by functionally related serine/threonine kinases." (PMID 25101980, 2014).
Ataxia (70 papers, 2000 to 2025). Ataxia refers to impaired coordination of voluntary muscle movement. "Ataxia–telangiectasia (OMIM#208900) is an autosomal recessive cerebellar ataxia linked to ATM gene variants, primarily characterized by cerebellar ataxia, oculocutaneous telangiectasia, and oculomotor apraxia." (PMID 40724495, 2025). "Ataxia-telangiectasia (AT) AT is a rare autosomal recessive disorder secondary to biallelic mutations of the ataxia-telangiectasia mutated (ATM) gene." (PMID 39456197, 2024). "Irradiation in presence of the small molecule inhibitor KU-60019 demonstrated that this upregulation is dependent on ATM (Ataxia telangiectasia mutated) activation." (PMID 39358789, 2024). "The patient with the ATM variant reports some improved effect on their ataxia after alpha-lipoic acid administration." (PMID 35719373, 2022). "The mutation in ATM was found in exome sequencing, but the genetic cause remained unclear in the seven other patients that were analyzed for 562 ataxia-causing genes." (PMID 34600502, 2021). "The main activators of DDR are two phosphoinositide 3-kinase-like kinases: ATM (Ataxia Telangiectasia Mutated) and ATR (ATM and Rad3-related)." (PMID 33198069, 2020). "Mutations in ataxia-telangiectasia-mutated (ATM) cause a severe syndrome characterized by a hypersensitivity to ionizing radiation, neurodegeneration, and ataxia." (PMID 32630049, 2020). "Six of these candidate variants were located in genes related to ataxia phenotype including ATM, GALC, SPTBN2, SYNE1, and TWNK." (PMID 31455392, 2019). "Identification of putative ATR (Ataxia telangiectasia and Rad3 related), ATM (Ataxia telangiectasia mutated), mTOR (mechanistic Target of Rapamycin) and DNA-PKcs (DNA-dependent protein kinase, catalytic subunit) Leishmania major protein sequences." (PMID 30265735, 2018). "ATM mutations cause Ataxia Telangiectasia (A-T) characterized by ataxia due to loss of Purkinje and granule cells in the cerebellum." (PMID 28620865, 2017). "Animals with combined ATM and Aprataxin (Aptx) deficiencies, which cause high basal levels of DNA damage and genome instability recapitulate the human AT syndrome and develop neurodegeneration and debilitating ataxia." (PMID 40859031, 2025). "Recent studies have explored therapies such as N-acetyl-DL-leucine for ataxia symptoms, bone marrow transplant therapy to restore immune competence, and gene therapy to correct defective alleles in the ATM gene—potentially restoring ATM protein function and reducing DNA damage." (PMID 40597142, 2025). "The results indicate interesting mutations in SETX and ATM genes that may be the leading cause of ataxia." (PMID 39281240, 2024). "USP2-null mice show impaired motor coordination and balance, so its deficiency in an ATM-null cerebellum might contribute to ataxia pathogenesis." (PMID 37830614, 2023). "Double inactivation of Pol β and ataxia telangiectasia mutated (ATM) results in cerebellar ataxia." (PMID 35794098, 2022). "This novel animal model provides a new tool to test mechanistic hypotheses regarding how ATM deficiency causes cerebellar pathology and ataxia." (PMID 34723800, 2021). "This patient was also found to harbour a variant of unknown significance in exon 5 ATM [Ataxia‐Telangectasia Mutated] (c.483G > C, p.GIn161His)." (PMID 31592449, 2019). "TRA1 is a representative of a group of proteins that include DNA-dependent protein kinase catalytic subunit, ATM (Ataxia telangiectasia mutated) and TRRAP (transformation/transcription domain-associated protein), with the carboxyl-terminal regions related to phosphatidylinositol 3-kinases." (PMID 26263547, 2015).